IL4 (interleukin 4)
Diseases named in the same sentence as IL4 in open-access papers (continued):
Sharing a sentence is not in itself a finding about the gene and the disease.
asthma (continued). "Atopic diseases such as atopic dermatitis, allergic rhinitis, and asthma involve an uncontrolled type 2 inflammatory response mediated by the Th2 cytokines IL-5, IL-13, and IL-4." (PMID 34238943, 2021). "In a murine model of asthma, neutralization of the Th2 cytokines IL-4 and IL-13 increased Th17 cell number and neutrophilic inflammation in the lung." (PMID 35387016, 2021). "Given the association of IL-4, IL-5, IL-9, IL-13 and TSLP to asthma pathologies, all have been targeted with antibody-based therapeutics that bind either directly to the cytokines or their receptors." (PMID 34680614, 2021). "The Reactome pathway analysis showed that MGMD prevents asthma mainly through regulation of the IL-4 and IL-13 signaling and the specialized pro-resolving mediators (SPMs) biosynthesis." (PMID 33968984, 2021). "This review aims to discuss the role of dupilumab, a human anti-interleukin-4 receptor α subunit monoclonal antibody that blocks both IL-4 and IL-13 signaling in severe asthma." (PMID 34572281, 2021). "In this sense, the role of dupilumab, a monoclonal antibody blocking IL-4 and IL-13 signaling pathway by inhibiting IL-4R alpha, is promising for the management of patients with asthma with reduced response to corticosteroids, as reviewed recently." (PMID 33816533, 2021). "In our previous study, we developed a four‐way gene model including IL13 rs20541, IL4 rs2243250, ADRB2 rs1042713, and FCER1B rs569108 for determining asthma susceptibility in Chinese Han children." (PMID 33277970, 2021). "Eosinophils are regarded as crucial biomarkers of allergic response and are closely related to inflammatory cytokines, including IL-4, -5, and -13, during the progression of asthma." (PMID 34055011, 2021). "Omalizumab, dupilumab, and tezepelumab can directly modulate the ASM in asthma, by specifically blocking the interaction between IgE, IL-4, and TSLP, and their receptors are located on the surface of ASM cells." (PMID 34572466, 2021). "In a murine asthma model, glycoproteins from Sphingomonas induced type 2 inflammation via natural killer T cells in an IL-4-, IL-13-, and IL-33-dependent manner." (PMID 33831071, 2021). "NF-κB induces the expression of various pro-inflammatory cytokines, including IL-4 and IL-17, which are the cytokines pivotal to the development of immune and inflammatory responses in asthma." (PMID 34071080, 2021). "Many asthma-relevant cytokines, including IL-4, IL-5 and IL-13, depend on JAK signaling to elicit an inflammatory response." (PMID 34680614, 2021). "Among those biomarkers, monoclonal antibodies against IL-4 and IL-5 have been developed for the treatment of asthma." (PMID 34516405, 2021). "As the common receptor for both IL-4 and IL-13 signaling, blockade of IL-4 receptor alpha (IL-4Rα) has been touted as a method of alleviating asthma symptoms and severity." (PMID 33653328, 2021). "Several studies have suggested that pro-inflammatory cytokines, such as IL-13 and IL-4, which are involved in the pathogenesis of asthma, contribute to the degradation of ZO-1 and occluding." (PMID 33868003, 2021). "In particular, IL-4 is considered to act predominantly in the early phase of asthma development through its role in regulating T cell proliferation and survival, and IgE synthesis." (PMID 33976140, 2021). "p38 is able to induce the differentiation and activation of Th2 in asthma, resulting in the facilitated release of cytokines (IL-4, IL-5, and IL-13) secreted by Th2 cells." (PMID 34629023, 2021). "Here, we demonstrated that Bru-34 markedly restored the Th1/Th2 immune imbalance in asthma by lowering the level of IL-4 and IL-4/IFN-γ ratio in BALF of allergic mice." (PMID 33859559, 2021). "T2-high (IL-4–, IL-5–, IL-13–driven) asthma is typified by eosinophilic inflammation, while T2-low disease has been linked to neutrophilia and molecular signals such as type 1 IFN and IFN-γ." (PMID 34591794, 2021).
asthma (continued). "In contrast, asthma pro-inflammatory cytokines such as IL-4, IL-5, IL-13, and IL-33 contribute to maintain the lean state." (PMID 33418879, 2021). "In children affected by severe asthma biologics targeting IgE, IL-5 and against IL-4 and IL-13 receptors are already available, and they have also been applied in CRSwNP." (PMID 34943362, 2021). "Whereas IL-13 has been a therapeutic target for asthma with ongoing clinical trials, dupilumab, anti-IL-4Rα which inhibits both IL-4 and IL-13 signalling, has been a front-runner treatment showing efficacy in severe asthma patients." (PMID 34127548, 2021). "Nevertheless, in a mouse model of B. tropicalis house-dust-mite asthma, a significant up-regulation of IL-4 and IL-13 production was noted among lung-infiltrating Vγ1 γδ T cells." (PMID 33661375, 2021). "In asthma, Th2 cytokines IL-4, IL-13, and IL-5 play a major role in stimulating airway inflammation, whereas Th1 cells suppress airway hyperreactivity by producing IFN-γ." (PMID 33781317, 2021). "Asthma is a chronic inflammatory disease, and Th2 cells, such as IL-4, IL-5 and IL-13, play key roles in asthma pathobiology." (PMID 35011278, 2021). "Gene Expression Omnibus (GEO) data sets revealed that Fbp1 was overexpressed in a murine model of asthma and in interleukin (IL)‐4‐ or IL‐13‐stimulated bronchial epithelial cells." (PMID 33960626, 2021). "In asthma, the release of Th2 cytokines, including IL-4 and IL-13, allows macrophage polarization towards an M2 phenotype." (PMID 33478047, 2021). "In the current study, we aimed to investigate the expression of Fbp1 in a murine model of asthma and interleukin (IL)‐4‐stimulated or IL‐13‐stimulated airway bronchial cell lines." (PMID 33960626, 2021). "Studies have suggested that SHP has a positive effect on the immune outcomes of asthma, such as reducing interleukin 4 (IL-4) and significantly increasing IFN-γ." (PMID 32727619, 2020). "IL-33 is mainly secreted by the airway epithelium and evidenced to exacerbate the Th2-mediated inflammation via further promoting the secretion of IL-4, IL-5, and IL-13 in allergic patients with asthma." (PMID 32650472, 2020). "The Th2 response plays a significant role in asthma, leading to interleukin-4 (IL-4), IL-5, and IL-13 production, IgE-mediated responses, mucus secretion and airway hyperreactivity (AHR)." (PMID 32620122, 2020). "For example, the main constituent of Nigella sativa oil, thymoquinone, stimulates IFN-γ production and decreases IL-4 production in animal models of asthma." (PMID 33339167, 2020). "Therefore, to resolve the mentioned confining factors about the IL4 gene -589C/T polymorphism, the present most up-to-date meta-analysis was conducted to determine a bona fide estimation of the association between IL4 gene -589C/T polymorphism and susceptibility to asthma." (PMID 33087044, 2020). "In eosinophil-dominant severe asthma, anti-IL-4Rα mAb, which blocks both IL-4 and IL-13 signaling, strongly reduced acute exacerbations and increased lung function." (PMID 32326200, 2020). "Dupilumab is profoundly involved in the amelioration of asthma by specifically binding to IL-4Rα shared by the IL-4 and IL-13 receptor complexes, inhibiting their signaling." (PMID 32019141, 2020). "SIRT1 is a key regulator of GATA3 via its deacetylation, and in T-lymphocytes from patients with severe asthma, a decrease in SIRT1 has been linked to increased expression of IL-4 via increased GATA3 activation." (PMID 32823491, 2020). "The most common and studied asthma phenotype is type 2 (T2) asthma characterized by type 2 cytokines interleukin (IL)-4, − 5 and − 13, whereas different immune cells and mediators drive the inflammation in the less studied type 17 (T17) asthma." (PMID 32560723, 2020). "RG-II isolated from Panax ginseng induced the Th1/Th2 immune response and IFNγ expression in mice with ovalbumin-induced asthma, while IL-4 and GATA3 expression and eosinophil populations were decreased in the bronchoalveolar lavage fluid." (PMID 32326081, 2020).
asthma (continued). "Oral administration of WG or RG alleviated IL-4, IL-5, and IL-13 expression and immune cell infiltration in the bronchoalveolar regions of mice with ovalbumin-induced asthma." (PMID 32326081, 2020). "IFNs and IL-4 have opposing roles in the immune response, with IFNs promoting an antiviral Th1 response and IL-4 driving a Th2 response characterized by asthma and allergy." (PMID 32635475, 2020). "Nevertheless, ginseng extracts alleviate allergic disorders such as asthma, allergic rhinitis, AD, and pruritus by inhibiting IgE, IL-4, and IL-5 expression through the modulation of mast cells, eosinophils, and Th1-to-Th2 ratio." (PMID 32326081, 2020). "For instance, Th2 cells secrete cytokines such as IL-4, IL-5, and IL-13 and play important downstream roles in the pathogenesis of asthma." (PMID 32580518, 2020). "Asthma is a chronic inflammatory airway disease in which interleukin-4 (IL-4), IL-13, and TNF-α are involved." (PMID 32139393, 2020). "Using multiplex xMAP technology, we have further validated that the levels of the upstream cytokines of S1P signaling such as IL-13, IFN-γ, TNF-α, IL-4, IL-5, and IL-1β were increased in the serum of asthma patients." (PMID 32637407, 2020). "While the anti-inflammatory effects of IL13 prevent lipopolysaccharide-induced lethality and IgG immune complex-induced lung injury in vivo, the proinflammatory function of IL13 in conjunction with IL4 play a key role in the pathophysiology of asthma." (PMID 33506093, 2020). "To study the effect of Tespa1 on STAT6 pathway, we detected the changes in IL-4 and IL-13 in the BAL of asthmatic mouse model, and the results showed that IL-4 and IL-13 in Tespa1−/− mice significantly increased compared with those in the WT asthma group." (PMID 33228696, 2020). "It turned out that the mRNA expressions of several inflammatory factors, such as tumor necrosis factor (TNF), Muc5ac, IL-4, IL-13, and IL-12b were significantly upregulated in asthma group compared with control and diacerein groups." (PMID 33013396, 2020). "In this study, experiments have confirmed that Tespa1 negatively regulates mast cells during asthma, and this event is related to the IL-4/STAT6 signaling pathway." (PMID 33228696, 2020). "Immunological treatment with monoclonal antibodies against anaphylactic IgE or against type 2 cytokines such as IL-5 and IL-4/IL-13 is another way to control asthma symptoms." (PMID 32391011, 2020). "In our study, CB2 agonist administration in OVA-induced asthma was found to reduce the accumulation of eosinophils, IL-4, IgE and TNF-α, although CB2 antagonist application found no reduction in the amount of these substances." (PMID 32922464, 2020). "The relationships between periostin, TSLP, eosinophils, and IL-4 in asthma point to the links between periostin–TSLP and the Th2 response." (PMID 33203095, 2020). "In a previous study, the NLRP3 inflammasome was shown to regulate M2 polarization via the upregulation of IL-4 in asthma." (PMID 33182702, 2020). "It was reported that LA decreased the level of Th2 production of IL-4 and IL-5 in an asthma mouse model." (PMID 32719431, 2020). "Most patients with concomitantly elevated levels of sputum eosinophils, periostin, and TSLP also had also increased IL-4 and IL-13 concentrations (6/7 patients for both cytokines, which represents 50% of the asthma group)." (PMID 33203095, 2020). "Very strong correlations between local periostin, TSLP, eosinophils, and IL-4 in asthma point to the link between periostin–TSLP and Th2 response." (PMID 33203095, 2020). "Studies in animals and in vitro models have demonstrated multiple biological properties of honokiol, including anti-asthma (through IL4 and IFN-NF-kB)." (PMID 33071794, 2020). "An increasing body of evidence has demonstrated that C33T of the IL-4 gene untranslated region (UTR) of chromosome 5q was associated with elevated serum IgE levels and the risk of asthma." (PMID 33228581, 2020).
asthma (continued). "Subsequent work has confirmed that blockade of the shared IL-4 and IL-13 receptor subunit IL-4Rα is highly effective in relieving the symptoms of asthma." (PMID 32485866, 2020). "Many asthma relevant micro-organisms induce the production of pro-inflammatory cytokine including IL-4, IL-13, and TGF-β, which are well known as contributors to the pathogenesis of asthma." (PMID 31979396, 2020). "We addressed the role played by IL-4-producing cells in aggravating asthma, using NOD IL-4KO mice sensitized and challenged with HDM (NOD IL-4KO HDM)." (PMID 33643284, 2020). "The alpha subunit of the IL-4 receptor (dupilumab), that blocks both IL-4 and IL-13 pathways, has resulted in reduction of asthma morbidity, while the use of the anti-IL-4R failed in phase II." (PMID 32194407, 2020). "It is well recognized that asthma is an immune response driven by Th2 and Th17 cells with cytokines such as IL-4, IL-5, IL-9, IL-10, IL-13, and IL-7 playing important roles." (PMID 33123005, 2020). "In the lungs of patients with asthma, Th2 cells secrete excess IL-4, IL-5, and IL-13 to inhibit the expression of Th1 cells, which reduces IFN-γ secretion." (PMID 32244835, 2020). "Compared with control and sham acupuncture groups, electroacupuncture upregulates IFN-γ and downregulates IL-4 and IL-10 in bronchoalveolar lavage and pulmonary tissue in asthma rodent model." (PMID 33144870, 2020). "The IL-4 induce airway remodeling encountered in asthma by its role in the proliferation of bronchial fibroblasts, myofibroblasts, and airway smooth muscles." (PMID 33228581, 2020). "The findings suggested that OVA exposure contributed to the remarkable elevation of IL-4, IL-5, IL-13, and IL-17A level in asthma group mice compared with control group mice." (PMID 33013383, 2020). "Functional analysis of disease components yielded all eight GOIs in the respiratory disease category (asthma and/or bronchiolitis and/or viral infections), with two genes (IL4 and IL13RA2) specifically in the COPD/asthma category." (PMID 33526116, 2020). "In this study, we examined the levels of IL-4, IL-5, and IL-21, which are involved in the pathology of asthma." (PMID 32143340, 2020). "It is worth mentioning that silver NPs have been shown to mitigate asthma and decrease the levels of IL-4, IL-5, IL-13, and NF-κB in addition to lowering AHR in OVA-induced allergic inflammation mouse models." (PMID 32714326, 2020). "This study aimed to investigate the regulatory effect of Tespa1 on mast cells in the pathogenesis of asthma and its relationship with the interleukin (IL)-4/signal transducers and activators of transcription 6 (STAT6) signaling pathway." (PMID 33228696, 2020). "Onion bulb extract (OBE) has also been shown to effectively reduce airway inflammation, IL4, and IgE levels and induces oxidation in animal models of asthma." (PMID 33123005, 2020). "During asthma, there is a hyperactivity of Th2 responses, in which the cytokines of the type 2 immunity, such as IL-4, IL-5, and IL-13 promote the harmful inflammatory events in the airways." (PMID 33087044, 2020). "Both in vitro and in vivo studies have demonstrated a strong link between TSLP expression and the production of IL-4, IL-5, and IL-13, which are central in the development of a T2 phenotype in asthma." (PMID 33255348, 2020). "Mature ILC2 is known to produce Th2-type cytokines (IL-4, IL-5, IL-9, and IL-13) involved in the initiation of an adaptive immune response in asthma." (PMID 32395125, 2020). "Although anti-IL-5 treatment and anti-IL-4/IL-13 treatment are clinically available for treating eosinophil-dominant severe asthma, recent research has been mainly focused on molecules that are more upstream, such as thymic stromal lymphopoietin." (PMID 32326200, 2020). "Periostin, a matricellular protein produced by airway epithelial cells under the control of IL-4 and IL-13, is a key molecule linking TType2/eosinophilic airway inflammation and remodeling in asthma." (PMID 32824775, 2020).
asthma (continued). "For example, AD-MSC treatment decreases IL-4 levels, ameliorating allergic airway inflammation in a mouse model of asthma and increasing survival in mice with sepsis." (PMID 32867857, 2020). "In an RCT with children aged 6–18 years with asthma and allergic sensitization, CLA supplementation was associated with decreased peripheral blood mononuclear cell production of IFN-gamma and IL-4." (PMID 33339279, 2020). "IL-4 is the major effector cytokine in both alternative activation of macrophages and pathogenesis of asthma." (PMID 32024540, 2020). "Consistent with the results of Th cell subset in mice, the asthma group displayed higher levels of IL-4, IL-17, IL-6, and TGF-β mRNA expression and lower levels of IFN-γ and IL-10 mRNA in the splenocytes than the normal and PBS groups." (PMID 32549755, 2020). "Th2-type cytokines such as IL-4, when increased relative to Th1 cytokines (IFN-γ, IL-2), cause asthma and exercise-induced allergy and induce disease vulnerability." (PMID 32731626, 2020). "Accordingly, asthma induction also significantly decreased Treg-associated IL-10 and TGF-β production while significantly increasing Th2-associated IL-4, IL-5, and IL-13 production and Th17-associated IL-17 production (p < 0.05)." (PMID 33072079, 2020). "In T2-high asthma, airway inflammation is driven by the release of interleukin-4 (IL-4), interleukin-5 (IL-5) and interleukin-13 (IL-13)." (PMID 33352823, 2020). "These phenomena are accompanied by Th2 cell activation and release of various cytokines (IL-4, IL-5, and IL-13) and chemokines (eotaxin), which are involved in the development of asthma." (PMID 32605045, 2020). "Since the macrophages are the predominant cells in the lung during allergic asthma, and IL-4 is the key cytokine in both alternative activation of macrophages and pathogenesis of asthma, elucidating the role of M2a cells in asthma is a major concern." (PMID 32024540, 2020). "Interleukin-2 (IL-2) and interleukin-4 (IL-4) are overexpressed in the airways of patients with corticosteroid-resistant asthma." (PMID 32112175, 2020). "Since FeNO is a surrogate biomarker for Type2-high asthma, particularly a downstream molecule of IL-4/13, several trials to apply FeNO to a biomarker to predict the efficacy of asthma drugs targeting IL-4/13 have been performed." (PMID 32824775, 2020). "Perhaps a more interesting finding was that certain T-cell populations in asthma patients can produce both IL-17A and IL-4, and such cells appear to be a combination of Th17 (an immune response involving IL-17 and separate from Th1 and Th2) and Th2." (PMID 33526116, 2020). "Glucocorticoids are old anti-inflammatory drugs that have been shown to be very effective in treating asthma and can quickly inhibit the transcription of pro-inflammatory cytokines such as IL-2, IL-3, IL-4, IL-5, and IL-623." (PMID 32760206, 2020). "There is already a body of research showing that increased IL-4 production can exacerbate eosinophilia and allergen-induced asthma, at least in those instances where the disease is Th2-driven." (PMID 33526116, 2020). "Other studies in our laboratory demonstrated that doxycycline suppressed C. pneumoniae-induced IgE and IL-4 responses in PBMC obtained from patients with asthma." (PMID 32511255, 2020). "Our findings show that OBE treatment resulted in a significant reduction of IL-4 and IL-5 consistent with other studies and effects of drugs that mediate an anti-allergic/anti-asthma action." (PMID 33123005, 2020). "Additionally, IL4 gene polymorphisms, like promoter region (C + 33 T) SNP, and 3017 G/T SNP in intron 2, have been associated with IgE levels, which might be involved in the pathogenesis of asthma." (PMID 33087044, 2020). "The upstream regulator cytokines of S1P signaling such as IL-13, IFN-γ, TNF-α, IL-4, IL-5, and IL-1β were significantly (P < 0.01) increased in the serum of asthma patients compared the healthy controls." (PMID 32637407, 2020).